CTSC (cathepsin C)
Diseases named in the same sentence as CTSC in open-access papers (continued):
Sharing a sentence is not in itself a finding about the gene and the disease.
tumor (continued). "Cathepsin C is involved in tumor interactions with mast cells, lymphocytes, fibroblasts and macrophages, and uPA with fibroblasts and endothelial cells, respectively." (PMID 30669448, 2019). "The relative quantification of secreted proteins by spectral counting confirmed that CtsC is secreted from PyMT tumor cells in addition to several cysteine cathepsins, such as cathepsins B, Z(X), and L1(V) and asparaginyl endopeptidase." (PMID 29088746, 2017). "Mechanistically, the cathepsin C in tumor debris generated by anticancer therapy is phagocytosed by macrophages and drives CXCL1/2 and complement factor B production via activating the TLR4/NF-κB signaling pathway, subsequently promoting NETosis and impairing therapeutic efficacy." (PMID 41480760, 2026). "CTSC expression was significantly higher in HCC tissues than in adjacent non-tumour tissues." (PMID 42014946, 2026). "The protein CTSC in tumor debris induces CXCL1/2 and CFB expression." (PMID 41480760, 2026). "Besides, with the addition of recombinant CTSC or tumor debris, TLR4 was colocalized with RAB5 (the indicator of early endosome) in macrophages, consistent with the point that TRIF adaptor was preferentially activated in endosomes." (PMID 41480760, 2026). "In vitro studies revealed that CTSC promotes tumor progression in ESCC." (PMID 40740774, 2025). "Subsequently, we analyzed the expression of CTSC in epithelial cells of tumor and normal samples." (PMID 40740774, 2025). "Notably, we found that CTSC exhibited the highest expression in malignant cells with worse prognosis in scRNA-seq data, and its expression was also the highest in TCGA tumor samples." (PMID 40740774, 2025). "In addition, multicolor immunofluorescence (mIF) analysis of tumor tissues showed that the protein levels of CTSC as well as the protein level of fibroblast marker α-SMA were significantly lower in the sh-CTSC group compared with the sh-NC group." (PMID 40740774, 2025). "For example, tumor cell-secreted protease cathepsin C (CTSC) could recruit neutrophils to form neutrophil extracellular traps (NETs), thereby promoting breast-to-lung metastasis." (PMID 39308692, 2024). "Antigens derived from tumor tissues can activate CD8+ T cells to produce anti-cancer responses, improving pore formation in target tumor cell membranes and subsequent target-cell killing by secreting cathepsin C, perforin, and granulysin to fusion target cell membranes." (PMID 36171887, 2022). "Co-culture experiments with tumor cells and NETosing neutrophils have hinted toward tumor-supplied factors, such as G-CSF, IL-8, or cathepsin C, but deeper mechanistic insights are needed to dissect contributions from developmental and diurnal neutrophil states." (PMID 35522219, 2022). "Given that cystatin F also inhibits cathepsin C in mice, this supports the hypothesis that cystatin F plays a role in the tumor microenvironment." (PMID 33868254, 2021). "Previous studies have shown that CTSC plays an important role in the regulation of autophagy, which may also be the mechanism of promoting tumor death." (PMID 33946049, 2021). "Correlation analysis showed that positive CTSC expression was positively associated with aggressive clinicopathological features, including increased tumour number, large tumour size, absence of tumour encapsulation, microvascular invasion and advanced TNM stage." (PMID 42014946, 2026). "Further investigation demonstrated that differentially upregulated genes in tumor-associated mCAFs (matrix-associated cancer-associated fibroblasts) were significantly enriched in the PI3K pathway, suggesting that CTSC-high cells promote mCAF proliferation through PDGFA ligand-mediated regulation." (PMID 40740774, 2025). "Moreover, CTSC was found to promote tumor progression in ESCC." (PMID 40740774, 2025). "To validate the expression of CTSC in ESCC using the TCGA database, we enrolled ESCC patients and collected both tumor tissues and adjacent normal tissues." (PMID 40740774, 2025).
tumor (continued). "The PR3-IL-1β-NF-κB axis, driven by cathepsin C, also contributes to p38 activation and ROS generation, leading to NET formation to support the metastatic growth of tumor cells." (PMID 41303697, 2025). "Another cathepsin, cathepsin C (CTSC), involved in the formation of neutrophil serine proteases (NSPs, neutrophil serine proteases), the components of NETs, secreted by the tumor promotes BC metastasis to the lungs via NETs, among others." (PMID 41019086, 2025). "These SEs showed strong correlations with key genes involved in immunosuppression and tumor progression, including SPP1, RAC1, CTSC, and SMS." (PMID 40725473, 2025). "On the other hand, pRCC showed upregulation of TFPI2, FSTL1, FAS, and PIGR in the epithelial/tumor, C1QTNF3 and GRN in the endothelial, and ITGAX, HLA-DQA1, IL4I1, and CTSC in the immune compartments." (PMID 38703764, 2024). "The qRT−PCR analysis revealed that upregulated expression of CTSC, CDCA8, and G6PD, whereas downregulated expression of CXCL9 in HCC compared with adjacent tumor tissue and normal liver cell lines." (PMID 38742112, 2024). "The proteinase 3 inhibitor sivelestat diminishes the tumor-secreted protease cathepsin C-induced activation of PR3-IL-1β-NF-κB-mediated recruitment of neutrophils and NETosis, thus further inhibiting NET-dependent colonization of tumor cells." (PMID 38023616, 2023). "Cathepsin C (CTSC) produced by cancer cells has also been reported to induce recruitment and activation of IMCGL in 4T1 tumor bearing-mice." (PMID 35309358, 2022). "Therefore, CTSC might promote tumor development by inhibiting cell senescence." (PMID 33946049, 2021). "Animal studies have shown inhibition of tumor metastasis by blocking NET formation with the application of small molecule drugs such as DNase, CTSC inhibitors, PAD4 inhibitors and NE inhibitors." (PMID 34204148, 2021). "Although these studies have discovered CTSV and CTSC involved in tumor progression, the intracellular signaling cascades linking the Pra-B regulate the levels of CTSV and CTSC in RCC cells for further investigation." (PMID 32331211, 2020). "Cathepsin C(CTSC), a lysosomal cysteine protease abundantly expressed in multiple tissues and belonging to the papain superfamily, plays a pivotal role in numerous tumor biological processes." (PMID 38742112, 2024). "In the present study, the expression of CTSS and CTSC was also detected in cancerous ovaries of hens, suggesting that CTSS and CTSC may also play roles in the angiogenesis and invasion of tumor cells." (PMID 20727192, 2010). "Moreover, treating neutrophils cultured in tumor cell-conditioned medium with Sivelestat (a PR3 inhibitor), Cl-amidine (a PAD4/histone citrullination inhibitor), or DNase I (which degrades NETs) effectively blocked NET formation and cathepsin C activity." (PMID 41303697, 2025). "The RT-qPCR result revealed that ALOX12 was markedly up-regulated (P=0.0144) and RMND5B was markedly down-regulated (P=0.0016) in tumor samples compared with controls, while the expression of CTSC was not notably different (P=0.7259) between tumor and control samples." (PMID 38903709, 2024). "Therefore, we conducted RT-qPCR to further verify the results and found that CTSC expression was higher in tumor samples and cells than in normal human astrocytes, which once again confirmed the accuracy and reliability of our study." (PMID 35109832, 2022). "Furthermore, CTSC was markedly overexpressed in tumor samples compared to normal tissues." (PMID 40740774, 2025). "The tumor volume and tumor weight of mice in the sh-CTSC group were significantly lower than those in the group with sh-NC (negative control), suggesting that knockdown of CTSC could effectively inhibit tumor growth." (PMID 40740774, 2025).
cancer (34 papers, 2006 to 2025). A tumor composed of atypical neoplastic, often pleomorphic cells that invade other tissues. "Cathepsin-related proteins have been broadly implicated in cancer, and we even previously reported CTSC as being a target in the suppression of RCC migration and invasion." (PMID 32331211, 2020). "Recent work has revealed that specific stimuli such as HMGB1 and CTSC initiate distinct signaling modules, underscoring the context-dependent heterogeneity of NETosis across infection, autoimmunity, thrombosis, and cancer." (PMID 41335221, 2025). "In summary, these findings demonstrated that CTSC functions as an oncogenic factor, driving cancer cell proliferation and migration while inhibiting apoptosis in ESCC." (PMID 40740774, 2025). "Not only that, some studies have shown that cancer cells can release lysosomal enzymes (e.g. Cathepsin C, CatC) through exocytose to promote the degradation of the extracellular matrix, increase angiogenesis potential." (PMID 37986192, 2023). "Nevertheless, within 7 days after inoculation, cathepsin C-enhanced cancer cells had been existed in lungs at the early time points." (PMID 35719975, 2022). "Bioluminescent imaging analyses showed that cathepsin C-induced elevation of cancer cell signal in lungs was already prominent at the first week after intravenous inoculation, indicating a role of cathepsin C in the early stage of metastatic colonization." (PMID 35719975, 2022). "We found that inhibition of CTSC increases cell senescence, and previous studies have reported that high state of senescence inhibits the development of cancer." (PMID 33946049, 2021). "Studies have implicated that overexpression of CTSC and CTSV expression in various different malignant tumors, such as breast ductal carcinoma, colorectal carcinomas, and pancreatic, and it was suggested to be associated with poor prognosis in HCC." (PMID 32331211, 2020). "Among miR-204 gene targets that are potential regulators of cell-matrix interaction and proteolysis, overexpression of APRC1B, CTSC, FAP, MMPs, BMP1, CDH11 and ITGB4 is associated with cancer metastasis and/or poor prognosis." (PMID 20369013, 2010). "Previous studies have reported that the CTSC gene is overexpressed in many cancers." (PMID 35109832, 2022). "In addition to its important physiological functions, CTSC is also involved in the regulation of various pathological mechanisms of cancer." (PMID 35109832, 2022). "Aging-related genes such as CTSC and ARNTL are associated with several cancers." (PMID 33946049, 2021). "In addition, other stefins, CtsB and CtsC, actively regulate cancer cell proliferation." (PMID 35563761, 2022). "Inhibition of cathepsin C (e.g., AZD7986) further limits protease activation, reducing tissue damage in sepsis and cancer models." (PMID 41335221, 2025). "Ex vivo, inflammatory molecules released from cancer cells [e.g., IL‐8/CXCL8, granulocyte colony‐stimulating factor (G‐CSF), CXCL1, CXCL2, Cathepsin C, and Toll‐like receptor (TLR) ligands] can induce NETs." (PMID 39865544, 2025). "CTSC, also known as DPP-1, has been the focus of many studies as a target for the treatment of various diseases, including cancer." (PMID 36831614, 2023). "GSEA showed that CTSC expression is involved in the ECM receptor interaction pathway, Toll-like receptor signaling pathway, and cancer cell signaling pathways, which are known to promote the malignant progression of various cancers." (PMID 35109832, 2022). "Praeruptorin B was found to potently inhibit migration and invasion of the RCC cells, as evidenced by decreased production of cathepsin C (CTSC) and cathepsin V (CTSV) proteins, proteases that regulate cancer cell invasion extracellularly." (PMID 35805049, 2022). "Previous studies of this project have shown that CTSC and RMND5B are cancer-promoting factors." (PMID 38903709, 2024).
cancer (continued). "In addition, we predicted the sensitivity of common anti-cancer drugs on prognostic signature, including CCR5, HMOX1, CTSC, CD5, BCL3, CDH1, TYROBP and CD38." (PMID 38767825, 2024). "Single-cell analysis identified that CTSC and B2M were up-regulated in LNM-positive epithelial cells with strong correlation to poor DFS, suggesting that cancer-related signaling pathways such as TNF-α/p38 MAPK signaling pathway could promote LNM in PTC." (PMID 34805166, 2021). "In this model, cathepsin C, but not cathepsin B, released from stromal cells was shown to be responsible for cancer development and angiogenesis." (PMID 30897858, 2019). "Interestingly, expression of cathepsin C was also increased in RIP1-Tag2 and MMTV-PyMT mammary gland models of cancer but had no functional role in their progression." (PMID 30897858, 2019). "Interestingly, cancer exosomes, but not normal exosomes, modulated expression of matrix remodelling (EFEMP1, DDK3, SPARC), cell cycle (EEF2K), membrane remodelling (LAMP2, SRPX), differentiation (SPRR2E), apoptosis (CTSC), transcription/translation (KLF6, PUS7)." (PMID 30008265, 2018).
infection (16 papers, 2014 to 2025). The state of being infected such as from the introduction of a foreign agent such as serum, vaccine, antigenic substance or organism. "A loss of CTSC function increases susceptibility to infections frequently seen in PLS patients, e.g., furunculosis, pyodermia, liver abscess, pneumonia, and others." (PMID 36554029, 2022). "Dipeptidyl peptidase 1 (cathepsin C) and cathepsin S were increased 1.53 and 1.71 fold respectively at 24 hours post infection." (PMID 40665229, 2025). "Cathepsin C, D, and L were reported to play important roles during immune response against pathogen infection in shrimp or crayfish." (PMID 34438618, 2021). "Via immunoblotting, we also observed reduced abundance of cathepsin C at 3 days post-infection." (PMID 40274809, 2025). "Supporting this, examination of proteome Z-scores indicated an increase in the abundance of cathepsin proteases during infection, with the exceptions of cathepsin C (CTSC) which showed a small reduction, and cathepsin B (CTSB), which was dramatically decreased." (PMID 40274809, 2025). "CTSC therefore plays a critical role in the protective inflammatory responses during infection, and some pathogens, such as Helicobacter pylori, are known to impair CTSC expression to promote infection." (PMID 38791530, 2024). "We did not observe a decrease in other proteases of the cathepsin family except for a slight reduction, but not complete absence, in cathepsin C expression at 3 days post infection." (PMID 40274809, 2025). "Consequently, loss-of-function mutation of CTSC in PLS resulting in a lack of PR3 leads to the deficit of antimicrobial and immunomodulatory functions of LL-37 in the gingiva, allowing for infection with A. actinomycetemcomitans and contributing to the development of severe periodontal disease." (PMID 36554029, 2022).
genetic disorder (3 papers, 2014 to 2025). "In this genetic disorder, we found loss-of-function mutations in the cathepsin C gene, which is highly expressed in immune cells and epithelial tissues." (PMID 41462866, 2025). "Patients with the rare genetic disease Papillon–Lefèvre syndrome (PLS) have loss of function mutations in the CTSC gene, which codes for DPP1." (PMID 40174958, 2025).
neuromuscular disease (1 paper, 2023). "Being part of the dipeptidyl dipeptidases family, the activities of dipeptidyl peptidase I, also known as Cathepsin C (DPP1 or CTSC, EC 3.4.14.1), and DPP4 are associated with neuromuscular diseases." (PMID 37108335, 2023).
CTSC also shares sentences with these, for which no sentence is quoted: diffuse palmoplantar keratoderma (3 papers); Immunodeficiency (3); Aggressive periodontitis (2); chronic obstructive pulmonary disease (2); gingivitis (2); keratodermas (2); ovarian cancer (2); Sjögren’s syndrome (2); abdominal aortic aneurysm (1); airway hyperresponsiveness (1); anaphylaxis (1); ANCA-associated vasculitis (1); Anxiety (1); autosomal recessive disease (1); brain injury (1); brain tumor (1); chronic kidney disease (1); Crohn disease (1); demyelination (1); diabetic nephropathy (1); Diffuse palmoplantar hyperkeratosis (1); emphysema (1); endometrial cancer (1); genodermatosis (1); hyperphosphataemia (1); inflammation (1); inflammatory bowel disease (1); Insulin resistance (1); kidney disease (1); liver failure (1).
A further 19 diseases each share a sentence with CTSC in 1 paper.